NPRL2 (NPR2 like, GATOR1 complex subunit)
Diseases named in the same sentence as NPRL2 in open-access papers (continued):
Sharing a sentence is not in itself a finding about the gene and the disease.
prostate carcinoma (4 papers, 2020 to 2025). A carcinoma that arises from epithelial cells of the prostate gland. "These conclusions are consistent with a previous report showing that NPRL2 expression is upregulated in prostate cancers and linked to poor prognosis and another showing that NPRL2 depletion inhibits proliferation of prostate cancer cells." (PMID 38915098, 2024). "In addition, NPRL2 was found to be significantly upregulated in docetaxel-resistant prostate cancer cells and associated with decreased mTOR signaling and elevated autophagy; depleting NPRL2 in these cells increases sensitivity to docetaxel by inducing apoptosis." (PMID 38915098, 2024). "Other studies also have shown that NPRL2 promotes chemoresistance in prostate cancer by activating autophagy." (PMID 39932765, 2025). "Along with these studies on prostate cancer, our study supports the idea that NPRL2 is required for cancer cell survival and proliferation in some contexts." (PMID 38915098, 2024). "NPRL2 is also known as tumor suppressor candidate 4, which is upregulated in primary prostate cancer tissues." (PMID 34376795, 2022). "In addition, high expression of NPRL2 has been linked to poor prognosis in patients with prostate cancer, and NPRL2 expression level is known to be upregulated in prostate cancer cell lines." (PMID 38915098, 2024). "Importantly, NPRL2 overexpression was shown to promote proliferation and docetaxel chemoresistance of prostate cancer cells through a mechanism that involves inhibition of the mTOR pathway." (PMID 38915098, 2024).
colon cancer (3 papers, 2017 to 2025). "Overexpression of NPRL2 in colon cancer cells increased the sensitivity to a topoisomerase I inhibitor, irinotecan (CPT-11), by activating the DNA damage checkpoints." (PMID 41469472, 2025). "Our data are in agreement with recent results concerning NPRL2 overexpression in colon cancer cells lines HT29 and HCT116, which leads to cell cycle arrest in G1 phase and apoptosis." (PMID 29127423, 2017).
colorectal cancer (2 papers, 2025). A primary or metastatic malignant neoplasm that affects the colon or rectum. "NPRL2 overexpression also suppresses tumor growth in colorectal cancer cell lines and xenograft mice, increasing sensitivity to 5-fluorouracil and oxaliplatin." (PMID 41469472, 2025).
epilepsy syndrome (2 papers, 2021 to 2022). A syndrome that has a characteristic cluster of clinical features and/or lectroencephalographic (EEG) findings that reflect underlying epileptic activity. "Epilepsy syndrome caused by NPRL2 and NPLR3 variations is similar to DEPDC5." (PMID 34376795, 2022).
familial focal epilepsy (2 papers, 2018 to 2022). "Only recently, new genes for familial focal epilepsy (FFE) have been reported from the GATOR1 pathway (DEPDC5, NPRL2, NPRL3) and these were missing from earlier versions of the gene panel CHE-46, CHE-76, CHE-85)." (PMID 29760947, 2018).
hepatocellular carcinoma (2 papers, 2025). A malignant tumor that arises from hepatocytes. "Reduced expression or deletion of NPRL2 was found in many cancers including lung, renal, colorectal, glioma, gastric, and hepatocellular carcinoma, and has been closely correlated with poor clinical outcomes." (PMID 39932765, 2025). "Conversely, the efficient down-regulation of NPRL2 protein expression by both the shRNA and siRNA systems enhanced proliferation, migration, and colony formation in vitro as well as significantly increased tumor growth in hepatocellular carcinoma." (PMID 39932765, 2025).
osteosarcoma (2 papers, 2017 to 2019). A usually aggressive malignant bone-forming mesenchymal neoplasm, predominantly affecting adolescents and young adults. "The expression of NPRL2 is negatively correlated with the survival rate of osteosarcoma patients, and it has important value as a prognostic factor of osteosarcoma." (PMID 30936265, 2019).
renal carcinoma (2 papers, 2008 to 2010). A carcinoma arising from the epithelium of the renal parenchyma or the renal pelvis. "For example, NPRL2/G21 demonstrated growth inhibition in vitro in small cell lung cancer cell line U2020 and renal carcinoma cell line KRC/Y cells almost 90%." (PMID 18725949, 2008). "The decrease or absence of NPRL2/G21 expression was detected in some SCLC, NSCLC and renal cancer cell lines using Northern blot analysis." (PMID 20193080, 2010).
squamous cell carcinoma (2 papers, 2010 to 2015). A carcinoma arising from squamous epithelial cells. "The expression of all three TSGs were significantly different between NSCLC subtypes: RASSF1A and FUS1 expression levels were significantly lower in squamous cell carcinoma (SCC), and NPRL2/G21 in adenocarcinoma (AC)." (PMID 26112163, 2015). "Strong suppression of both, NPRL2 and RBSP3 was seen in 100% of cases already at Stage I of squamous cell carcinomas." (PMID 20193080, 2010).
channelopathy (1 paper, 2018). Channelopathies are a group of diseases caused by the dysfunction of ion channel subunits or their interacting proteins. "Discovery of mutations in DEPDC5, NPRL2, and NPRL3 that encode for GATOR1 (negative modulator of mTORC1) have pioneered the channelopathy-independent approach in understanding the pathological process of NFLE." (PMID 30319421, 2018).
cortical dysplasia (1 paper, 2023). "The authors proposed a molecular subregional effect, according to which variants closer to the NPRL2/NPRL3 binding site (where DEPDC5 binds to exert its inhibitory effect on the mTOR pathway) may lead to more severe phenotypes featuring cortical dysplasia." (PMID 36067010, 2023).
depression (1 paper, 2022). "Our metabolite analysis of the NPRL2 nKO brain show significantly lower levels of the neurotransmitter dopamine, which is linked to depression." (PMID 35165201, 2022).
Intellectual disability (1 paper, 2023). "Baldassari in 201918 reported 83 patients with “language or speech delay” or “intellectual disability” out of 183 (45%), among which 75 had DEPDC5 mutations (48% of total DEPDC5 variant—155), 4 NPRL2 (40% of NPRL2 variants—10), and 4 NPRL3 (4/18, 22% of NPRL3 variants—18)." (PMID 37491868, 2023).
pleural tumors (1 paper, 2010). "The pleural tumors from the mice treated with LacZ along with cisplatin or NPRL2 weakly stained for γ-H2AX." (PMID 20700484, 2010).
polymicrogyria (1 paper, 2025). A developmental brain abnormality characterized by an excessive amount of small convolutions on the surface of the brain and cognitive dysfunction. "Interestingly, a pathogenic, maternally inherited variant in NPRL2 has been reported in another individual with EE‐SWAS and polymicrogyria." (PMID 40944498, 2025).
prostate tumors (1 paper, 2024). "Similar trends of NPRL2 expression were also observed in prostate tumors and corresponding normal tissues (p < 0.001)." (PMID 38915098, 2024). "We evaluated the mRNA expression level of NPRL2 in lung and prostate tumors using data from the The Cancer Gemone Atlas (TCGA) and Genotype-Tissue Expression (GTEx) datasets." (PMID 38915098, 2024).
stomach adenocarcinoma (1 paper, 2025). "A bioinformatics analysis in stomach adenocarcinoma found a negative correlation between ImmuneScore, StromalScore, and ESTIMATEScore and expression of NPRL2." (PMID 39932765, 2025).
stomach cancer (1 paper, 2025). "A number of T cell co-inhibitory molecules CTLA4, ICOS, CD274, PDCD1, and IDO were markedly downregulated by NPRL2 treatment which was in agreement with the data found in bioinformatics analysis in stomach cancer patients' samples." (PMID 39932765, 2025).
viral infections (1 paper, 2026). "Our findings reveal a precise mechanism by which NPRL2 antagonizes PRRSV by targeting a critical viral protein for autophagic degradation, highlighting the therapeutic potential of harnessing the host's ubiquitin-autophagy pathway to combat viral infections." (PMID 41742285, 2026).
tumor (17 papers, 2008 to 2025). "The percentage of myeloid-derived suppressor cells (MDSC) and CD163+ tumor-associated macrophages (TAM) were markedly downregulated in tumors expressing NPRL2, whereas the numbers of HLA-DR+ DC cells were significantly increased." (PMID 39932765, 2025). "The expression of CD68 and CSF1 associated with tumor-associated macrophages (TAM) were significantly downregulated in NPRL2-treated samples." (PMID 39932765, 2025). "Restoration of NPRL2 exhibited significantly slower tumor growth in humanized-mice, which was associated with increased presence of human cytotoxic-T, and DC and decreased percentage of Treg, MDSC, and TAM in TME." (PMID 39932765, 2025). "Overexpression of NPRL2 in NPRL2-deficient and cisplatin-resistant NSCLC cells reactivated the cellular response to cisplatin and promoted tumor suppression activity in vitro and in mouse models, which might be linked to the role of overexpressed NPRL2 in promoting DNA damage and ROS production." (PMID 41469472, 2025). "Interestingly, early reports have implicated NPRL2 as a tumor suppressor gene." (PMID 19521502, 2009). "Individual mouse growth curve showed that after 3 wk of treatment, NPRL2 contained a tumor size below 500 mm3 for 50% of mice (4/8), whereas control, anti-PD1, and combination were 0% (0/9), 11% (1/9), and 25% (2/8)." (PMID 39932765, 2025). "Restoration of NPRL2 expression altered tumor microenvironment (TME), induced apoptosis, inhibited cell growth, and signaling." (PMID 39932765, 2025). "In this study for the first time, it has shown that the tumor suppressor gene, NPRL2, can induce significant antitumor immune responses by altering the tumor immune microenvironment and overcoming anti-PD1 resistant tumors." (PMID 39932765, 2025). "Bioluminescence images showed the visual differences in tumor burden in the lung between NPRL2-treated and empty vector-treated mice." (PMID 39932765, 2025). "Restoration of NPRL2 is multifunctional including inducing apoptosis in cancer cells to inhibit tumor growth." (PMID 39932765, 2025). "The percentage of change in tumor intensity between pre-and post-treatment was significantly different in the NPRL2 treated group vs control (p<0.04)." (PMID 39932765, 2025). "Later, many reports confirmed the role of NPRL2 as a tumor suppressor not only in NSCLC, but also in renal, ovarian, colorectal, breast, and other cancers." (PMID 41469472, 2025). "Bioluminescence imaging on mice showed that 7 out of 10 mice contained an extremely low amount of tumor burden in the NPRL2 treatment group, which was completely and visually different than in the control or pembrolizumab group." (PMID 39932765, 2025). "NPRL2 (Nitrogen Permease Regulator-Like 2) is also known as TUSC4, a tumor suppressor gene, located on chromosome 3p21.31 in a cluster with other tumor suppressor genes including TUSC2/FUS1." (PMID 39932765, 2025). "The effect of NPRL2 gene therapy, a tumor suppressor gene, on innate and adaptive immune cells in tumors has not been previously studied." (PMID 39932765, 2025). "To identify the anti-tumor immune cellular mechanism of NPRL2, we evaluated the antitumor effect of NPRL2 on LLC2 syngeneic tumors after depleting cytotoxic CD8+ T, CD4+ T, NK, and antigen-presenting macrophages and dendritic cells in mice." (PMID 39932765, 2025). "Overexpression of NPRL2 in NPRL2-deficient and cisplatin-resistant NSCLC cells reactivated cellular response to cisplatin treatment and promoted tumor suppression activity in vitro and in mouse models." (PMID 41469472, 2025). "As NPRL2 induced apoptosis in tumor cells, we were interested to see antigen presentation by DCs and their maturation." (PMID 39932765, 2025). "Altogether, our study shows a novel approach of NPRL2 tumor suppressor gene therapy in sensitizing immunotherapy-resistant tumors." (PMID 39932765, 2025).
tumor (continued). "Stably expressing NPRL2 clones from A549 and H1299 cells were generated, and their impact on tumor growth was assessed in humanized mice." (PMID 39932765, 2025). "Nitrogen permease regulator-like 2 (NPRL2/TUSC4) is known to exert both tumor-suppressing and oncogenic effects in different types of cancers, suggesting that its actions are context dependent." (PMID 38915098, 2024). "The overexpression of NPRL2 in NPRL2-deficient and cisplatin-resistant NSCLC cells reactivates cellular response to cisplatin and promotes tumor suppression activity in vitro and in mouse models." (PMID 37445831, 2023). "Despite a similar growth in vitro (not shown), when the cells were implanted subcutaneously to NSG mice, tumor development was faster for control MM1.S than TSC2 and NPRL2 KO variants." (PMID 36400754, 2022). "At the N-terminus, another indirect relationship is found with nitrogen permease regulator-like 2 (NPRL2), a tumour suppressor that regulates Tor." (PMID 23329412, 2013). "Next, the cell cycle in tumor cells treated with NPRL2 and cisplatin was analyzed by flow cytometry (FACS) with use of a APO-BRDU KIT." (PMID 20700484, 2010). "Activated Chk1 and Chk2 increase the expression of cell cycle checkpoint proteins, including Cdc25A and Cdc25C, leading to higher levels of G2/M arrest in tumor cells treated with NPRL2 and cisplatin than in tumor cells treated with cisplatin only." (PMID 20700484, 2010). "The cell cycle in tumor cells treated with NPRL2 and cisplatin was analyzed by flow cytometry (FACS)." (PMID 20700484, 2010). "The down-regulated Chk2 expression attenuated NPRL-2-induced apoptosis and its ability to sensitize the tumor cells' response to cisplatin." (PMID 20700484, 2010). "NPRL2/Gene 21 (GenBank accession #AF040707), which is 1351 bp long and encodes a protein of 380 amino acid residues, is one of the tumor suppressor genes identified in a 120-kb homozygous deletion region on human chromosome band 3p21.3." (PMID 20700484, 2010). "The tendency of more frequent decrease of NPRL2 mRNA level with tumor progression was seen only for AC cases, where Spearmen's coefficient of reverse correlation (rs) between tumor Stages (I, II, III) and expression R values was 0.47 (P = 0.06)." (PMID 20193080, 2010). "In this study, we tested the hypothesis that NPRL2 which induces apoptosis and DNA damage in tumor cells, would promote a variety of innate and adaptive immune responses and exert a strong antitumor effect in overcoming anti-PD1 resistance in KL mutant tumors." (PMID 39932765, 2025). "Together, these studies suggest that NPRL2 may play distinct roles in different histopathological subtypes, tumor stages, or patients with different characteristics." (PMID 38915098, 2024). "Loss of a genomic locus (3p21.3) containing NPRL2 and decreased NPRL2 expression are observed in many cancer cell lines and tumor tissues, suggesting that the protein may have tumor suppressive functions." (PMID 38915098, 2024). "Previously obtained results indicated that NPRL2/G21 is a multiple tumor suppressor gene." (PMID 20193080, 2010). "Moreover, tumor cells treated with NPRL2 and cisplatin have a remarkably high number of TUNEL-positive cells compared with those treated with cisplatin alone in an orthotopic model of cisplatin-resistant pleural dissemination." (PMID 20700484, 2010). "Consistent with our previous studies, NPRL2 delivery induced apoptosis and inhibited colony formation in an array of anti-PD1 moderately (H1299) or resistant cells (A549, LLC2) as well as inhibited tumor growth in syngeneic, immune deficient, and immune-competent humanized mouse models." (PMID 39932765, 2025). "NPRL2 stable clones in A549 and H1299 NSCLC cells were generated and developed tumors in humanized mice for tumor microenvironment analysis." (PMID 39932765, 2025).
tumor (continued). "Consistent with this gene expression data, tumor-promoting immune suppressive immune cells Treg, MDSC, and TAM were significantly downregulated in NPRL2++/++ tumors in humanized mice." (PMID 39932765, 2025). "Resistance to cisplatin has been initially observed in yeast S. cerevisiae for Npr2 and Npr3 deletion mutants (NPRL2 and NPRL3 homologs, respectively), years before GATOR1 components were suggested to be tumor suppressors." (PMID 41469472, 2025). "When comparing TCGA-lung tumors and GTEx-normal lung tissues, we found that NPRL2 expression was significantly lower both in lung tumors and the adjacent normal tissues than in normal lung tissues (p < 0.001), suggesting that NPRL2 may play a tumor suppressive role in lung tumor development." (PMID 38915098, 2024). "Some of these genes, e.g., RASSF1, NPRL2, and SEMA3B, suppress the growth of tumor cells in vitro and in vivo." (PMID 25961819, 2015). "NPRL2/G21 (nitrogen permease regulator-like 2 gene), also known as TUSC4 (tumour-suppressor candidate 4), is a tumor suppressor gene commonly expressed in normal tissues, including lung tissue." (PMID 26112163, 2015). "NPRL2 (human ortholog of NPR2) and DEPDC5 (human ortholog of IML1) have been reported to function as tumor suppressors." (PMID 23705068, 2013). "With NotI microarrays we tested how often LUCA (NPRL2, RASSF1A) and AP20 (RBSP3) regions were deleted or methylated in the same tumor sample and found that this occured in 39% of all studied samples (P < 0.05)." (PMID 20193080, 2010). "A significant expression decrease (≥2) was found for all three genes early in tumor development: in 85% of cases for RBSP3; 73% for NPRL2 and 67% for RASSF1A (P < 0.001), more strongly pronounced in squamous cell than in adenocarcinomas." (PMID 20193080, 2010). "With NotI microarrays we also tested how often LUCA (NPRL2 and RASSF1A) and AP20 (RBSP3) regions were deleted or methylated in the same tumor and found that this occurred in 58% of all studied cases (18 of 26)." (PMID 20193080, 2010). "Until now TSGs which were isolated from AP20 and LUCA regions (e.g.G21/NPRL2, RASSF1A, RASSF1C, SEMA3B, SEMA3F, RBSP3) were shown to inhibit tumour cell growth both in vitro and in vivo." (PMID 18725949, 2008). "Using GIT and growth analysis under cultural conditions we have shown that FUS1, SEMA3B, G21/NPRL2, RASSF1A, RASSF1C, RBSP3 (genes from AP20 and LUCA regions) and other TSGs inhibit tumour cell growth both in vitro and in vivo." (PMID 18725949, 2008). "The TME was significantly altered when NPRL2 was permanently restored, which was characterized by increased pro-immunogenic signatures including increased TILs, CD8+ T, and HLADR+ DC, which led to significantly reduced tumor growth in humanized mice." (PMID 39932765, 2025). "NPRL2 showed a strong antitumor effect by inhibiting tumor growth significantly when no immune cells were depleted." (PMID 39932765, 2025). "Expression of NPRL2/TUSC4, a tumor-suppressor gene, is reduced in many cancers including NSCLC." (PMID 39932765, 2025). "NPRL2 treatment is still effective in inhibiting tumor growth in the absence of NK cells, suggesting NK cells are not essential for the NPRL2-mediated antitumor effect." (PMID 39932765, 2025). "Moreover, the simultaneous down-regulation of RBSP3, NPRL2 and RASSF1A in the same tumor sample was observed in 39% of all cases." (PMID 20193080, 2010). "In SCID mice both genes either did not permit tumour formation or in growing tumours they were inactivated (for NPRL2 it was 10 mice and for RASSF1A it was 8 mice)." (PMID 18725949, 2008).